RSPO4 (R-spondin 4)
Diseases named in the same sentence as RSPO4 in open-access papers (continued):
Sharing a sentence is not in itself a finding about the gene and the disease.
tumor (continued). "Intriguingly, we found that RSPO4 suppressed Wnt/β-catenin signaling in both LGR4 and LGR5 expressing tumor cells." (PMID 41522353, 2026). "Consistently, luciferase reporter assay showed that RSPO4 FUm1/2 mutant lost the inhibitory effect on Wnt/β-catenin signaling and target genes in both LGR4+/LGR5- and LGR4-/LGR5+ tumor cell lines." (PMID 41522353, 2026). "In this study, we found that RSPO4 suppressed EMT and tumor cell stemness through Wnt/β-catenin signaling in an LGR4/5 dependent manner." (PMID 41522353, 2026). "By sphere formation assay, we found that FUm1/2 mutant expression lost the inhibitory effect of RSPO4 on cancer cell stemness of both LGR4+/LGR5- and LGR4-/LGR5+ tumor cells." (PMID 41522353, 2026). "RSPO4 functions as a tumor suppressor by antagonizing canonical and non-canonical Wnt signaling in an LGR4/5- and ZNRF3- dependent manner." (PMID 41522353, 2026). "RSPO4 also induced significant suppression of the transcriptional activities of critical Wnt/β-catenin target genes CCND1, c-MYC and MMP7, which play important roles in tumor cell metastasis." (PMID 41522353, 2026). "Indeed, we observed very strong expression of RSPO4 and LGR6 in the mesenchymal cells and epithelial components of the tumor, respectively." (PMID 34099859, 2021). "We wondered why RSPO4 antagonizes, rather than potentiates, Wnt signaling in tumor cells." (PMID 41522353, 2026).
cancer (4 papers, 2021 to 2026). A tumor composed of atypical neoplastic, often pleomorphic cells that invade other tissues. "In this study, we systematically evaluated RSPO4 expression status in a variety of cancers, and further evaluated its functions and underlying mechanisms in cancer stemness and metastasis." (PMID 41522353, 2026). "By mining mutation data from COSMIC and TCGA, we found that RSPO4 also underwent truncating and homozygous point mutations, indicating its loss-of-function effect in cancers and genetic diseases." (PMID 41522353, 2026). "We also analyzed the association between RSPO4 methylation and clinical features in cancer patients from TCGA datasets." (PMID 41522353, 2026). "In addition, by analyzing the overall survival using KM-plotter 53 and PrognoScan 54, we found that lower RSPO4 expression was significantly associated with worse overall survival in patients with different types of cancer." (PMID 41522353, 2026). "Therefore, RSPO4 methylation is associated with poor prognosis and clinicopathological features of cancer patients." (PMID 41522353, 2026). "We further found that RSPO4 is readily expressed in human normal tissues, but frequently downregulated or silenced in multiple cancer types due to its promoter CpG methylation." (PMID 41522353, 2026). "Through analyzing TCGA datasets using DNMVID 49, we found that RSPO4 exhibited significant higher methylation level in multiple types of cancer tissues than their corresponding normal tissues." (PMID 41522353, 2026). "We previously explored methylated TSG candidates for multiple types of human cancers through CpG methylomic study 45, 46, and identified RSPO4 as a methylated target." (PMID 41522353, 2026). "By analyzing TCGA datasets using Sangerbox 51, we found that mRNA expression of RSPO4 was significantly lower in multiple cancer tissues than the corresponding normal tissues." (PMID 41522353, 2026). "Through analyzing the TCGA datasets, we found that RSPO4 was frequently methylated in a variety of TCGA cancer cohorts, with genomic deletions also exist occasionally." (PMID 41522353, 2026). "Treatment with RSPO4 CM or stimulation with exogenous recombinant human RSPO4 protein induced an inhibitory effect on Wnt/β-catenin signaling in cancer cells." (PMID 41522353, 2026). "Interestingly, downregulation of RSPO4 in cell lines induced a strong inhibition of activated forms of the focal adhesion-associated proteins including Fak, Paxillin, and Src which are major signaling molecules involved in the regulation cancer cell stiffness and cell locomotion/migration." (PMID 36611933, 2022). "Demethylation of RSPO4 promoter in cancer cell lines was also confirmed by BGS analysis." (PMID 41522353, 2026). "Thus, LGR4/5 and ZNRF3 are required for RSPO4-induced suppression of Wnt/β-catenin signaling in cancer cells." (PMID 41522353, 2026). "Through analyzing whole-genome CpG methylation profiles (methylomes) by methylated DNA immunoprecipitation (MeDIP)-chip and double-enzyme reduced representation bisulfite sequencing (dRRBS) 45, we identified RSPO4 as a methylated gene in cancer cell lines as well as tissues." (PMID 41522353, 2026). "We also performed flow cytometry to check whether RSPO4 expression can induce cancer cell apoptosis." (PMID 41522353, 2026). "We hypothesized that RSPO4 may exert an effect on actin remodeling in cancer." (PMID 41522353, 2026). "Preclinical studies using established PTC cell lines support that RSPO4 overexpression is associated with BRAF V600E mutation and is a critical upstream event that promote activation of kinases of focal adhesion signaling known to drive cancer cell locomotion and invasion." (PMID 36611933, 2022). "Therefore, RSPO4 provides another therapeutic target for inhibiting EMT and cancer stemness." (PMID 41522353, 2026). "Therefore, RSPO4 expression results in the downregulation of both canonical and non-canonical Wnt signaling in cancer cells." (PMID 41522353, 2026).
infection (1 paper, 2016). The state of being infected such as from the introduction of a foreign agent such as serum, vaccine, antigenic substance or organism. "Since we were unable to detect Rspo4 at steady state or throughout the course of infection, we did not pursue Rspo4 in any further experiments." (PMID 27046199, 2016).
RSPO4 also shares sentences with these, for which no sentence is quoted: lung carcinoma (2 papers); ovarian cancer (2); asthenia (1); atherosclerosis (1); bladder cancer (1); colorectal cancer (1); genetic diseases (1); nasopharyngeal carcinoma (1); prostate carcinoma (1); tooth agenesis (1); triple-negative breast carcinoma (1).